KRT8 (keratin 8)
Diseases named in the same sentence as KRT8 in open-access papers (continued):
Sharing a sentence is not in itself a finding about the gene and the disease.
lung fibrosis (18 papers, 2020 to 2025). "Terminal differentiation from KRT8+ transitional cells to alveolar type-1 cells can cause aberrant persistence of regenerative intermediate stem cell states in human lung fibrosis." (PMID 35091537, 2022). "Keratin-8-positive progenitor cells were identified in a bleomycin induced pulmonary fibrosis model." (PMID 41302962, 2025). "Examining gene profiles in non‐resolvable COVID‐19 revealed increases in fibrotic gene and Krt8 expression similar to those in idiopathic pulmonary fibrosis." (PMID 40476695, 2025). "In bleomycin‐induced models of pulmonary fibrosis, Krt8+ cells showed increased expression of pro‐fibrotic proteins such as Areg and Hbegf and the presence of myofibroblasts." (PMID 40476695, 2025). "This was characterized by an increase in aberrant basaloid (Krt8) and/or basal cells (Krt5) and increased pulmonary fibrosis based on hydroxyproline content compared to control lungs." (PMID 40343336, 2025). "And second, stimulating fibroblast-to-myofibroblast transformation and the expression of pathologic ECM proteins by profibrotic KRT8+ cells that leads to lung fibrosis and inflammation." (PMID 39358385, 2024). "In this study, we show that IL11 is uniquely expressed by aberrant basaloid and KRT5-/KRT17+ cells in human lung fibrosis and by Krt8+ transitional cells in the fibrotic lungs of mice after bleomycin injury." (PMID 39358385, 2024). "The emergence of KRT8+ epithelial cells and spontaneous pulmonary fibrosis in human HPS patients is likely to result from the combined effects of genetic and environmental factors on AT2 cell function." (PMID 39699958, 2024). "This cell population is highly similar to the aberrant basaloid cells in IPF, but of transient character in bleomycin-induced lung fibrosis: Krt8+ ADI cells peak in the fibrotic phase and gradually disappear during resolution of fibrosis." (PMID 35326501, 2022). "The Krt8+ state appears in several independent models of lung injury and persists in human lung fibrosis, creating a distinct cell–cell communication network with mesenchyme and macrophages during repair." (PMID 32678092, 2020). "Specifically, as alveolar type 2 cells differentiate into alveolar type 1 cells, a transitional cell population of cells characterized by increased expression of Krt8 arises in animal models of pulmonary fibrosis." (PMID 33257409, 2020). "Indeed we observe increased bronchiolization based on Krt8 and Krt5 expression and increased pulmonary fibrosis based on hydroxyproline content in Adrp-CreERT2;Mycf/f;mTmG mice 6 weeks after bleomycin injury." (PMID 40343336, 2025). "KRT8 plays a key role in lung disease, such as lung fibrosis." (PMID 35664775, 2022). "In the bleomycin model of lung fibrosis, the conditional deletion of Il11ra1 in AT2 cells prevents the accumulation of profibrotic Krt8+ transitional cells, enhances alveolar epithelial regeneration, and protects against fibrosis." (PMID 39358385, 2024). "During the period of lung fibrosis, several intermediate AECII was detected by specific markers such as keratin 8 (KRT8), claudin 4 (CLDN4) and stratifin (SFN)." (PMID 37161570, 2023). "Building on their surprising finding that upon targeted analysis, SNPs in the KRT8 locus (but no other keratins) may be associated with a risk for pulmonary fibrosis (PF) in humans, the authors explore the time course of KRT8 expression in multiple injury models." (PMID 37966115, 2023). "Here, the authors present a single cell RNA-seq map of recovery from bleomycin lung injury in mice and uncover a Krt8+ transitional stem cell state that precedes the regeneration of AT1 cells and persists in human lung fibrosis." (PMID 32678092, 2020).
lung fibrosis (continued). "Notably, studies in mouse models of lung fibrosis and injury have identified similar converging differentiation pathways, namely from club cells on the one hand and AT2 cells on the other to a population called Krt8+ alveolar differentiation intermediate (ADI) cells." (PMID 35326501, 2022). "Using quantitative comparisons of the gene expression signatures measured in this study we found that this AT2 derived cell state is also very similar if not identical to the Krt8+ ADI cells discovered by us, suggesting that persistence of Krt8+ ADI may directly mediate progressive lung fibrosis." (PMID 32678092, 2020).
pancreatic cancer (16 papers, 2011 to 2025). "The same study showed that KRT8 was universally overexpressed in five solid tumour cancers (breast, colon, pancreatic, ovarian and lung) where high KRT8 expression was associated with poor prognosis in patients with pancreatic cancer." (PMID 35204653, 2022). "More recently, a genome-wide association study of 2039 patients in Japan identified a significant association between the KRT8 gene and pancreatic cancer." (PMID 35204653, 2022). "We employed single - cell analysis technology to thoroughly examine the binding of NAT10 and KRT8 to T - cell receptors, thereby gaining novel insights into the mechanism underlying NAT10 - regulated KRT8 - mediated immune suppression in pancreatic cancer through ac4C acetylation." (PMID 41203621, 2025). "In addition to its prognostic value, serum KRT8 showed potential as a diagnostic blood biomarker in discriminating between pancreatic cancer patients and healthy controls." (PMID 35204653, 2022). "Collectively, these findings highlight the critical role of KRT8 in promoting the malignant progression of pancreatic cancer." (PMID 41203621, 2025). "GEPIA revealed that KRT8 is highly expressed in pancreatic cancer tissues compared with normal tissues and is significantly associated with poor overall and disease-free survival." (PMID 41203621, 2025). "As expected, all three subtypes of cancer cells expressed the generic pancreatic cancer cell marker genes, such as Krt8 and Krt18." (PMID 37998349, 2023). "All these three cancer cell subtypes expressed the generic pancreatic cancer cell marker genes, such as Krt8 and Krt18." (PMID 37190324, 2023). "We determined the genes that express differently in pancreatic cancer tissues compared with normal tissues and associate with survival (P < 0.05) as Hub genes, yielding a total of six Hub genes, including S100A14, KRT8, KRT19, MAL2, MYO5B, and PSCA." (PMID 36522691, 2022). "LysoSM-induced cell migration is associated with increased elastic properties in PANC-1 pancreatic cancer cells and the perinuclear reorganization of keratin-8 intermediate filaments in PANC-1 pancreatic cancer cells and A549 lung cancer cells." (PMID 36230781, 2022). "qPCR analysis confirmed efficient knockdown and overexpression of KRT8 in pancreatic cancer cells." (PMID 41203621, 2025). "NAT10 may regulate the expression of adhesion molecules on the surface of tumor cells through KRT8, thereby leading to PD-L1-mediated immune evasion in pancreatic cancer." (PMID 41203621, 2025). "Notably, KRT8 is not only highly expressed in pancreatic cancer epithelial cells but also in certain macrophages and fibroblasts, suggesting its potential involvement in mediating intercellular interactions and signaling within the TME." (PMID 41203621, 2025). "To this end, we investigated whether KRT8 could affect malignant progression and the immune microenvironment of pancreatic cancer by examining its impact on aggressive progression and the immune microenvironment of pancreatic cancer." (PMID 41203621, 2025). "In conclusion, NAT10 promotes pancreatic cancer progression and immune evasion by regulating the ETS2-PD-L1 axis and stabilizing KRT8 mRNA, highlighting its potential as a therapeutic target for overcoming immunotherapy resistance." (PMID 41203621, 2025). "Functional assays demonstrated that KRT8 promoted pancreatic cancer cell proliferation, and CCK-8 assays revealed reduced viability upon KRT8 knockdown, and increased viability upon KRT8 overexpression." (PMID 41203621, 2025). "Our single-cell ligand-receptor bubble plot analysis showed that in pancreatic cancer epithelial cells, the expression levels of MIF, MDK, and LGALS9 were significantly higher when NAT10 and KRT8 were highly expressed than when they were low-expressed." (PMID 41203621, 2025).
pancreatic cancer (continued). "Single-cell RNA sequencing analysis revealed enhanced interactions between pancreatic cancer epithelial cells with high NAT10 and KRT8 expression, and T cells, thereby providing new insights into the immune microenvironment." (PMID 41203621, 2025). "Single-cell RNA sequencing analysis demonstrated enhanced interactions between pancreatic cancer epithelial cells with high NAT10 and KRT8 expression and T cells." (PMID 41203621, 2025). "As expected, epithelial markers (Krt7, Krt8, Krt18, Krt19, Epcam, Egfr, Cdh1) were highly expressed in primary pancreatic tumors and in the cancer cell line NB508 and nearly absent in the nonepithelial MEFs and in normal WBCs." (PMID 25242334, 2014).
hepatocellular carcinoma (12 papers, 2009 to 2026). A malignant tumor that arises from hepatocytes. "In hepatocellular carcinoma, the deletion of keratin 8 and keratin 18 promotes the proliferation, invasion, and metastasis of HepG2 cells by upregulating claudin 1 expression." (PMID 35789645, 2022). "Interestingly, an opposing regulatory pattern of these two cytoskeletal components in liver tissues has also been seen in patients with hepatocellular carcinoma where β-tubulin protein level was up-regulated and keratin 8 down-regulated." (PMID 20040084, 2009). "To test the seeded aggregation of KRT8, we aggregated monomeric KRT81–90 in the presence of liver tissue extracts from people with either ASH or hepatocellular carcinoma (HCC)." (PMID 35637421, 2022).
lung adenocarcinoma (12 papers, 2009 to 2025). A carcinoma that arises from the lung and is characterized by the presence of malignant glandular epithelial cells. "Elevated KRT8 expression in tumor tissues is significantly associated with increased IRP risk in lung adenocarcinoma patients receiving immunotherapy." (PMID 40777008, 2025). "In conclusion, our exploratory study provides preliminary evidence that KRT8 expression may serve as a predictive biomarker for IRP in lung adenocarcinoma patients treated with immunotherapy, while the underlying biological mechanisms remain to be elucidated." (PMID 40777008, 2025). "However, little is known regarding the effects of KRT8 on the pathological processes of lung adenocarcinoma (LUAD) and the prognostic values associated with its expression." (PMID 30634629, 2019). "This study demonstrated that elevated KRT8 expression serves as a significant biomarker for IRP development in lung adenocarcinoma patients receiving immunotherapy." (PMID 40777008, 2025). "This current study aims to examine KRT8 expression levels in lung adenocarcinoma patients undergoing immunotherapy, thereby providing a valuable tool for stratifying patients at heightened risk of developing IRP." (PMID 40777008, 2025). "This study aims to explore the correlation between KRT8 expression and IRP risk in lung adenocarcinoma patients receiving immunotherapy." (PMID 40777008, 2025). "In human lung adenocarcinoma, keratin 8 has been found to promote metastasis and epithelial-mesenchymal transition (EMT) through NF-κB signaling." (PMID 39739089, 2024). "Keratin 8 (KRT8) is a type II basic intermediate filament (IF) protein, which can be abnormally expressed in various human cancers (including lung adenocarcinoma tissue)." (PMID 34323652, 2021). "Notably, alterations in KRT8 expression have been observed across multiple cancer types, including lung adenocarcinoma, indicating its potential utility as a biomarker for disease progression and treatment response." (PMID 40777008, 2025). "Furthermore, a recent study has demonstrated that lung adenocarcinoma may develop through aberrant persistence of a keratin 8 + transitional stem cell state that can generate a distinct cell–cell communication network and dysregulate molecular checkpoints on differentiation." (PMID 39739089, 2024). "However, the role of KRT8 in lung adenocarcinoma (LUAD) remains unclear." (PMID 35664775, 2022). "In this study, by analyzing RNA-seq data from the Cancer Genome Atlas (TCGA)-lung adenocarcinoma (LUAD) and lung squamous cell carcinoma (LUSC), we have determined the expression profile of KRT8, and assessed its prognostic significance and the possible mechanism underlying the dysregulation." (PMID 30634629, 2019). "Previous work has shown that cytokeratins 7 and 8 (KRT7 and KRT8) can be targeted in lung adenocarcinomas, while white blood cells should have no cytokeratin expression." (PMID 29186152, 2017). "However, the relationship between KRT8 expression and IRP, particularly in the context of lung adenocarcinoma immunotherapy, has not been extensively explored." (PMID 40777008, 2025).
melanoma (12 papers, 2009 to 2025). A malignant, usually aggressive tumor composed of atypical, neoplastic melanocytes. "Western blot analysis also showed that apigenin caused partial reversal of EMT in melanoma cells, as evidenced by upregulation of keratin 8 and E-cadherin, and downregulation of fibronectin and N-cadherin." (PMID 26911838, 2016). "In our study, we found that the expression of KRT8 was higher in metastatic melanoma than primary melanoma in TCGA cohort, whereas it showed converse results in GSE46517 cohort." (PMID 33441834, 2021). "On the contrary, co-expression of keratin 8 and 18 together with vimentin leads to elevated invasion and cell migration in human melanoma." (PMID 23536778, 2013). "In melanoma, KRT8/18 was thought to be related to increased invasiveness and metastasis." (PMID 33441834, 2021). "Moreover, KRT8 has also been reported to be abnormally expressed in melanoma." (PMID 34737950, 2021). "When implanted in thymectomized mHM, which were subsequently engrafted with patient melanoma tissue (autologous, or mHMTA), sTOs expressed thymic tissue markers EPCAM, KRT5, and KRT8 and contained developing double-positive T cells." (PMID 41129601, 2025).
squamous cell carcinoma (12 papers, 2009 to 2025). A carcinoma arising from squamous epithelial cells. "Aberrant expression of KRT8 and KRT18 is associated with neoplastic progression and invasion in squamous cell carcinomas." (PMID 27711225, 2016). "For example, abnormal expression of KRT8 and KRT18 is related to tumor progression and invasion in squamous carcinomas." (PMID 36610719, 2023). "In contrast, only three genes (KRT8, KRT18, and GAPDH) correlate with significantly reduced OS of squamous cell carcinoma patients (N = 525), mirroring the histological classification of the murine KM tumours as adenocarcinoma." (PMID 31032816, 2019).
colon carcinoma (10 papers, 2005 to 2023). "The upreguation of TAGLN and downregulation of SOX9, IRS1, P15, AREG, IER5L, KRT8 in RKO, SW620 and CW2 colon cancer cells indicated these genes may be the target molecules for the biological behaviour of IGFBP-rP1 in colon cancer." (PMID 20977730, 2010). "We found that IGFBP-rP1 could upreguate TAGLN, downregulate SOX9, IRS1, P15, AREG, IER5L, KRT8 in these colon cancer cells, indicating that these genes may be the important IGFBP-rP1 responsible genes in colon cancer." (PMID 20977730, 2010).
prostate tumors (10 papers, 2011 to 2024). "We also observed that FKA inhibits Ubc12 neddylation, c-Myc, and keratin-8 expression in both CD44+/CD133+ prostate tumor spheroids and xenograft tumors." (PMID 35912174, 2022). "Our analysis of metastases in the Krt8-CreERT2 model suggests that larger lung tumors resemble the primary prostate tumors, expressing the AR at varying levels and Trp63 in a proportion of the cells." (PMID 29782499, 2018). "NE phenotype prostate tumor cells in TRAMP mice display similar morphological and molecular characteristics to human NED and NEPC cells, including the expression of IHC markers, synaptophysin, chromogranin A and FOXA2, and loss of expression of cytokeratin 8 (CK8)." (PMID 23620793, 2013). "Examination of invasive cancers from the Krt8-Cre model did not reveal any overt squamous differentiation, as seen in Apc;Tgfbr2 null mouse prostate tumors, for example." (PMID 29782499, 2018).
ovarian carcinoma (9 papers, 2010 to 2024). A malignant neoplasm originating from the surface ovarian epithelium. "Our focus was on elucidating the impact of EZMLD on m6A methylation modification of KRT8 in ovarian cancer cells and its subsequent role in regulating the FAS apoptosis signaling pathway." (PMID 39103890, 2024). "In ovarian cancer, Twist1 overexpression promotes the expression of N-cadherin and reduces the expression of keratin-8 and E-cadherin." (PMID 26356073, 2015). "In ovarian cancer patients, we found a hypomethylated m6A state of the KRT8 mRNA." (PMID 39103890, 2024). "Ultimately, our findings confirm that EZMLD induces apoptosis in ovarian cancer cells through the mechanism of METTL3 and METTL14 methyltransferases, which mediate KRT8 m6A methylation modification." (PMID 39103890, 2024). "In this study, we observed hypomethylation of m6A in KRT8 mRNA from ovarian cancer tissues, posttreatment with EZMLD led to a significant increase in m6A content in vivo and elevated m6A methylation of KRT8 mRNA in both in vitro and in vivo." (PMID 39103890, 2024). "Genes that contributed to the most variation between subtypes included known biomarkers and master regulators of ovarian cancer subtypes (MUC16 and PAX8) and many keratin and cadherin genes (KRT19, KRT7, KRT8, CDH6, and CDH1)." (PMID 39131380, 2024). "Except ovarian carcinoma-derived OVCAR cells, which expressed CDH1 and KRT8 but barely any of the analyzed mesenchymal markers, significant IGF2BP1 expression was only observed in mesenchymal-like tumor- or metastases-derived cells." (PMID 23677615, 2013). "We identified TF encoding genes that were putatively controlled by PEs common to the keratin group (KRT8, KRT13, KRT18), and are also previously reported to be at least 5-fold over-expressed in early and late stage ovarian cancer." (PMID 20181230, 2010). "Furthermore, the Amniota-specific KRT8, KRT19, KRT23 and KRT80 were shown to be up-regulated in ovarian cancer." (PMID 36949761, 2023). "Although some of the proteins identified in our ubiquitination dataset are known to be associated with ovarian cancer, such as CAP1, CRABP2, EPCAM or KRT8, their ubiquitination status has not been previously investigated in HGSC." (PMID 35292711, 2022). "Overexpression of Snail in ovarian cancer cells induced mesenchymal markers, such as tea-shirt zinc finger homeobox (TSHZ1), collagen type Vα, and fibrillin-1 (FBN-1), while suppressing E-cadherin, myosin-5C, keratin-18, keratin-8, annexin-A3, and suppressor of tumorigenicity 14 (ST14)." (PMID 26356073, 2015).